BDNF (brain derived neurotrophic factor)
Diseases named in the same sentence as BDNF in open-access papers (continued):
Sharing a sentence is not in itself a finding about the gene and the disease.
depression (continued). "The described link among BDNF and obesity, classical and non-classical CV risk factors in individuals with obesity and different degrees of depression provide one more explanatory variable (i.e., BDNF) as a culprit." (PMID 35911513, 2022). "This reduction in BDNF levels is maintained for weeks, in association with a greater oxidative stress as compared to animals not vulnerable to depression." (PMID 35326190, 2022). "We performed a variety of behavioral, molecular, and electrophysiological experiments on different mouse models to investigate whether C/EBPβ contributed to the HFD-induced depression-like behaviors by regulating the BDNF/AMPARs pathway." (PMID 36578534, 2022). "Taken together, these findings indicate that the BDNF/TrkB/ERK/CREB signaling pathway may be a potential therapeutic target for depression." (PMID 36014820, 2022). "The ‘neurotrophin hypothesis of depression’ is mainly based on evidence that antidepressant treatment improves BDNF expression, while a reduction in hippocampal BDNF levels is correlated with stress-induced depressive behaviors." (PMID 36499295, 2022). "Decreased neurotrophic support through chronic stress negatively impacts the survival of neurons and hampers the functions of the hippocampus, so BDNF may be involved in promoting the progression of depression symptoms." (PMID 35510613, 2022). "How might BDNF dysfunction play a more important role in the pathophysiology of depression in adolescents than in adults?" (PMID 35875661, 2022). "Regardless of the type of stress to which animals are exposed, decreased BDNF may affect many functions in the brain, such as neurogenesis, neuron survival, and neurogenesis, promoting the occurrence of depression-like behaviors in stressed animals." (PMID 36046834, 2022). "Thus, there are indications that antidepressant treatment increases BDNF in the brain in patients with depression." (PMID 35563389, 2022). "The neurotransmitter hypothesis of depression at the transcriptomic level can be tested using BDNF- and IDO1-knockout mouse models and RNA-seq." (PMID 35711916, 2022). "Inhaled pinenes may modulate the serotonergic, adrenergic, and dopaminergic systems in the brain as well as the expression of BDNF in the hippocampus that are involved in the pathogenesis of depression and anxiety." (PMID 36429972, 2022). "The primary objective of this prospective study was to verify whether the serum levels of S100B, BDNF, and proBDNF change with the successful treatment of depressive episodes among women with BD and MDD." (PMID 35448545, 2022). "In this study, we explored how miR-139-5p regulates depression and exerts its antidepressant-like effect via activating the BDNF-TrkB pathway and suggested the BDNF-TrkB pathway could be a new depression drug target (Fig. graphical abstract)." (PMID 35543383, 2022). "Anti-depressant treatments, whether pharmacological or psychosocial, restore BDNF levels in individuals with depression." (PMID 36311022, 2022). "The PREDIMED-NAVARRA randomized trial on 243 adults with depression has documented that the Mediterranean diet with virgin olive oil or nuts after 3 years of follow-up could slightly increase circulating BDNF concentrations." (PMID 36185667, 2022). "All these mentioned indicate that up-regulating BDNF level may have positive effect to the treatment of depression." (PMID 36158555, 2022). "Nerve cell plasticity is changed by neuronal injury and decreased brain-derived neurotrophic factor (BDNF) content, and dysregulation of the intestinal flora composition and function may result in metabolic abnormalities that lead to depression." (PMID 35991880, 2022). "Nevertheless, the results of the current study suggest that in a mouse model of depression (BDNF+/−), CXCL1 deletion and Slc17a7 reduction are related to the loss of excitatory neurons in the prefrontal lobe, whereas Ptbp1 downregulation correlates with neuronal regeneration." (PMID 35711916, 2022).
depression (continued). "Indeed, in depressed subjects practising physical exercise regularly, BDNF concentrations are regularized, and depression symptoms attenuated." (PMID 36035468, 2022). "Although decreased peripheral expression of BDNF certainly presents a risk of depression, we cannot find a definite relationship between the peripheral level of BDNF with depression to use BDNF as a reliable biomarker to assess the depression in clinical practice." (PMID 35510613, 2022). "The neurotrophic factor hypothesis suggests that stress-induced reductions in BDNF expression may lead to atrophy of the hippocampus and prefrontal cortex, which in turn may lead to depression." (PMID 36186850, 2022). "Studies have found that after rTMS treatment, the levels of BDNF in peripheral blood of patients with depression are higher than before, which may be one of the mechanisms of rTMS." (PMID 35711903, 2022). "In the present report, there was clear evidence of a negative association between BDNF and major clinical depression scores, with no impact of BDNF genetic polymorphisms." (PMID 35911513, 2022). "Stress and depression can intrude on the ability to fall asleep and maintain sleep; endorphins are hormones able to improve mood and sleep quality, and one of the most known is the Brain-Derived Neurotrophic Factor (BDNF)." (PMID 36035468, 2022). "BDNF affects neuronal integrity and neurogenesis and plays a vital role in depression." (PMID 36185927, 2022). "Xiaoyao pills also has anti-inflammatory effect, which may relieve depression symptoms by inhibiting inflammatory reaction or activating NGF/BDNF-TRKA/TrkB-CREB pathway." (PMID 36569324, 2022). "In addition to neuroprotection, BDNF plays a crucial role in depression and the therapeutic mechanisms of antidepressants." (PMID 34983570, 2022). "Moreover, DNA methylation at the promoter of brain-derived neurotrophic factor (BDNF) is currently being tested for the treatment of autism or depression." (PMID 39086963, 2022). "Animal model of depression revealed that BDNF signaling was rescued in the hippocampus after peripheral injection of BDNF for 14 consecutive days, and its mRNA level in the CA3 area of the hippocampus was also increased, suggesting the antidepressant-effect of BDNF." (PMID 36158555, 2022). "A study in rats with chronic unpredictable stress revealed that HJDT might be a latent Chinese medicine used for treating or alleviating complex symptoms of depression via the BDNF–TrkB–CREB pathway." (PMID 36499295, 2022). "However, we cannot find the correlation between the BDNF levels and the severity of depression in patients with endogenous depression." (PMID 35295780, 2022). "In this study, we tested the hypothesis that naringin, a natural medicinal compound, could promote adult hippocampal neurogenesis and improve depression-like behaviors via regulating the BDNF/TrkB/CREB signaling pathway." (PMID 35478969, 2022). "We speculate that the inhibition of CREB/BDNF pathway in hippocampus may be a necessary condition for the expression of depression, whether in neuropathic pain or LPS induced depression models." (PMID 35401106, 2022). "Then, it has been hypothesized that the altered BDNF levels observed in patients with depression are due to a reduced release from platelets which are considered one of the major circulation sources of BDNF." (PMID 35911513, 2022). "In addition to depression, deficits in BDNF signaling have been reported to contribute to several neuropsychiatric diseases, such as Huntington’s disease, Alzheimer’s disease (AD), schizophrenia and anxiety disorders." (PMID 36291673, 2022). "The use of turmeric could have positive effect on sexual function in some cases, since it is known to help increase BDNF and reduce inflammation, and thus also improve depression." (PMID 36135826, 2022).
depression (continued). "Exercise, providing positive responses and adaptations, might affect the circulatory levels of two neurotransmitters (serotonin and dopamine), upregulate the BDNF-Serotonin systems, and decrease anxiety and depression." (PMID 35409772, 2022). "Reduced levels of brain-derived neurotrophic factor (BDNF) lead to depression, according to the neurotrophic hypothesis of depression." (PMID 35056845, 2022). "However, dysfunction of BDNF/TrKB signaling leads to the impairment of synaptic transmission and depression-like behaviors." (PMID 36578534, 2022). "GMDZ regulated the 5-HTT and BDNF expression in the depression model." (PMID 35161241, 2022). "Chronic restraint stress (CRS) can lead to behavioral inhibition, anxiety, and depression-like behaviors, downregulate the expression of glucocorticoid receptors (GR), and weaken the release of glutamate induced by brain-derived neurotrophic factor (BDNF) in the PFC." (PMID 35663199, 2022). "The research revealed that 5-HTTLPR polymorphism, brain-derived neurotrophic factor (BDNF), extensive psychological demands, social stigma, and overtraining syndrome (OTS) may all contribute to a unique version of depression." (PMID 35878116, 2022). "Additionally, many studies have reported that a reduction in BDNF levels is a significant factor contributing to the occurrence of depression." (PMID 36014820, 2022). "Articles published between 2009 and 2022 related to biomarkers of depression were grouped into eight main clusters including “inflammation”, “fMRI”, “cytokines”, “machine learning”, “brain-derived neurotrophic factor”, “oxidative stress”, “metabolomics”, and “microRNAs”." (PMID 36186850, 2022). "This amino acid, by being metabolized into the 5-HT or Kyn pathway, assumes a crucial role in several aspects profoundly connected to depression’s physiopathology, such as neuroinflammation, chronic stress, dysregulation in the gut microbiota, and BDNF expression levels." (PMID 35955633, 2022). "The peptide BDNF is required for optimal neuronal function and seems to be lowered in depression." (PMID 35600820, 2022). "The neurotrophic effects of BDNF have been particularly studied in depression." (PMID 35344113, 2022). "Altogether these observations support the hypothesis that BDNF may be a common link among obesity, CV diseases and depression." (PMID 35911513, 2022). "Brain-derived neurotrophic factor (BDNF) plays an important role in the pathogenesis of depression." (PMID 35197855, 2022). "Subsequent findings suggest that chronic low-dose inflammation in PCOS may interact with BDNF to contribute to the development of depression." (PMID 36233452, 2022). "The current psychobiotic formulation (Lactobacillus helveticus R0052 and Bifidobacterium longum R0175) treatment for eight weeks significantly improved depression-like behavior by upregulating BDNF levels in patients with depression compared to the placebo group." (PMID 36499295, 2022). "Decreased serum BDNF may be involved in the pathophysiology of depression in Parkinson’s disease patients." (PMID 35743271, 2022). "In addition, patients with a history of depression had significantly decreased blood BDNF levels compared with healthy controls (SMD = −2.24, 95% CI = −4.90, −0.42; p = .000)." (PMID 35510613, 2022). "As such, pathological disruptions of BDNF may constitute the pathophysiology of neuropsychiatric disorders, such as depression, and result in behavioural abnormalities." (PMID 36499240, 2022). "The neurotrophic hypothesis of depression proposes that decreased levels of BDNF in the hippocampus lead to the pathogenesis of depression, and treatment with antidepressants enhances BDNF levels and alleviates depressive symptoms." (PMID 35754496, 2022). "However, it was found that BDNF-knockdown mice exhibited depression-like features based on reduced levels of neurotransmitter content." (PMID 35711916, 2022).
depression (continued). "For example, Lactobacillus helveticus NS8 and MCC1848 intake enabled the recovery of chronic and subchronic-stressed rodents from their state of depression through the modulation of the central 5-Hydroxytryptamine (5-HT) system and Brain Derived Neurotrophic Factor (BDNF) expression." (PMID 36558455, 2022). "Previous studies have shown that people with depression have lower levels of peripheral brain-derived neurotrophic factor (BDNF), which may contribute to the pathophysiology of depression." (PMID 35996095, 2022). "In summary, the present study found that stress-induced depression could cause hippocampus damage, elevation of serum CORT, decrease of neurotrophic factors (GR, p-GR, and BDNF) and Cx43 expressions, and increase of c-Src expression." (PMID 34984950, 2022). "BDNF is widely described as a factor involved in multiple cerebral processes in adult life with higher levels assumed to be protective for several diseases such as depression or Alzheimer‘s disease." (PMID 35736415, 2022). "RPS5KA is a downstream enzyme of BDNF that regulates gene expression and therefore may participate in the pathogenesis of depression." (PMID 35986314, 2022). "In a systematic review exploring targeted biomarkers for rTMS therapy, depression was associated with increased GABA and BDNF levels, chronic pain was associated with increased levels of b-endorphin, and post-stroke neurologic deficit associated with decreased BDNF levels." (PMID 35454957, 2022). "In this study, the BDNF was regarded as a biomarker of depression." (PMID 35624812, 2022). "In addition, many substances which are able to promote BDNF biosynthesis (xanthoceraside, L-701324, 1-methylnicotinamide, etc.)have been reported to protect against depression." (PMID 35959431, 2022). "In the univariate analysis, the severity of depression (BDI-II score) did not significantly associate with plasma BDNF levels (β = −0.009, SE = 0.005, p = 0.087), whereas this association became significant in multivariate analysis." (PMID 35911513, 2022). "We further explored whether FTO downregulation in ACC regulates anxiety- and depression-like behaviors through MMP-9/BDNF axis coordination in NP model." (PMID 35634463, 2022). "The neurodegenerative hypothesis of depression explains decreased hippocampal volumes and impairments of neurotrophic support by BDNF." (PMID 36142325, 2022). "Besides, we identified a novel inflammatory transcriptional factor C/EBPβ which played a core role in depression through downregulating BDNF, impairing synaptic function and promoting AMPARs internalization." (PMID 36578534, 2022). "An additional hypothesis posits that facial injection of BoNT/A1 causes structure or function changes in the brain to alleviate depression, possibly by upregulating brain derived neurotrophic factor (BDNF) expression in the brain (França and Lotti, 2017)." (PMID 35333944, 2022). "Additionally, in a French population of individuals who were 65 or older, those who had late-life depression also had elevated methylation of the BDNF gene, leading to a reduction in BDNF gene transcription." (PMID 35887357, 2022). "In particular, the high-flavonoid group might achieve a significant boost in the BDNF level, which corresponds with an improvement in depression." (PMID 36499295, 2022). "Altogether, by activating the BDNF-TrkB signaling pathway, miR-139-5p inhibition plays an antidepressant-like role and might serve as an effective depression target (Fig. graphical abstract)." (PMID 35543383, 2022). "The aim of the present study was to investigate associations between hippocampal subfield volumes and plasma levels of brain-derived neurotrophic factor (BDNF) in patients experiencing a first episode of major depression (MD) (n = 30) as compared to healthy controls (HC) (n = 49)." (PMID 35600081, 2022).
depression (continued). "In addition, it increased the serotonin, norepinephrine (NE), and BDNF levels in the hippocampus; additionally, a single strain of Bifidobacterium longum 1714 decreased stress, depression, and anxiety behaviors." (PMID 35204119, 2022). "Besides its involvement in multiple neurological disorders such as Alzheimer’s, Parkinson’s and Huntington’s disease, BDNF also participated in depression." (PMID 36578534, 2022). "The epigenetic modulation of BDNF and TRKb genes might contribute to the pathophysiology of depression and related behaviors." (PMID 35408474, 2022). "In reactive depression patients, the expression levels of BDNF may reflect the severity of depression." (PMID 35295780, 2022). "Taken together, we hypothesized that SIRT1 was a mediator of S-ketamine in increasing the BDNF level, and S-ketamine alleviated depression symptoms through the SIRT1-dependent BDNF pathway." (PMID 35664490, 2022). "We speculate that the inhibition of CREB/BDNF pathway in hippocampus may be a necessary condition for the expression of depression." (PMID 35401106, 2022). "Moreover, RAS, mainly Ang II, is involved in the pathological process of depression by promoting inflammation, oxidative stress, and stress responses and reducing BDNF levels." (PMID 36761172, 2022). "The alleviation of depression-like behaviours by IAA may be mediated by elevated concentrations of BDNF and 5-HT in the brain." (PMID 36501051, 2022). "However, the authors observed a potential improvement in serum BDNF levels and both treatment regimens appeared to improve baseline scores of the Center for Epidemiological Studies Depression Scale (CES-D), a screening instrument for depression." (PMID 35565814, 2022). "Depression raises blood corticosterone levels, lowers BDNF levels, and inhibits neurogenesis." (PMID 35668445, 2022). "We speculate that this has a lot to do with the current interest in depression and the strong link between depression and BDNF." (PMID 36291673, 2022). "Similarly, DHM treatment also upregulates BDNF expression and decreases the expression of proinflammatory cytokines in the hippocampus of rats with depression and diabetic neuropathic pain." (PMID 36496991, 2022). "The neurotrophic hypothesis of depression postulates that low levels of BDNF could induce atrophy at limbic structures and prefrontal cortex, whereas antidepressant treatment increases BDNF levels in depressed patients." (PMID 35370811, 2022). "The downregulation of BDNF and TrkB expressions in the hippocampus and cortex might lead to behavioural defects of depression and anxiety." (PMID 36362262, 2022). "It is also known to increase BDNF levels in young adults with depression symptoms." (PMID 36014776, 2022). "However, in atrophy, synaptic disconnection, and irregular functioning of depression circuits, BDNF has been shown to play an important role." (PMID 35510613, 2022). "In addition, a recent pilot study found that the probiotic administration of B. longum NCC3001 significantly improved depression in a cohort of individuals with IBS by upregulating BDNF." (PMID 36499295, 2022). "Formononetin is a type of isoflavone that upregulates the expression of the glucocorticoid receptor and brain-derived neurotrophic factor, protects neurons, and promotes neurogenesis in the hippocampus, thereby effectively reducing chronic corticosterone-induced depression-like behavior in mice." (PMID 36440424, 2022). "Central and peripheral levels of BDNF expression are lower in patients with MS and depression and this may be exacerbated during infection with COVID-19, as supported by findings that anti-depressant treatments and exercise training raise BDNF levels." (PMID 35492581, 2022). "Given that decreased levels of BDNF have been found to be related to depression in older patients, exercise may not only reverse but also prevent depressive symptoms by increasing BDNF levels." (PMID 35953521, 2022).